SLC47A2 (solute carrier family 47 member 2)
Description:
Multidrug efflux pump that functions as a H(+)/organic cation antiporter. Mediates the efflux of cationic compounds, such as the model cations, tetraethylammonium (TEA) and 1-methyl-4-phenylpyridinium (MPP+), the platinum-based drug oxaliplatin or weak bases that are positively charged at physiological pH, cimetidine, the platinum-based drugs cisplatin and oxaliplatin or the antidiabetic drug metformin. Mediates the efflux of endogenous compounds such as, creatinine, thiamine and estrone-3-sulfate. Plays a physiological role in the excretion of drugs, toxins and endogenous metabolites through the kidney. [Isoform 6]: Non-functional protein.
Synonyms: MATE2; FLJ31196; MATE2-K; MATE2-B; MATE2K
Tractability: Small molecule: a high-quality ligand is known; it belongs to a druggable protein family. Antibody: UniProt places it where antibodies can reach, with high confidence; its Gene Ontology location is reachable by antibodies, with high confidence; UniProt predicts a signal peptide or a membrane-spanning region. PROTAC: a small molecule that binds it is known.
Target class: Transporter; Electrochemical transporter; SLC47 family of multidrug and toxin extrusion transporters; SLC superfamily of solute carriers
Gene: Protein-coding gene on chromosome 17 (19,678,288 to 19,718,979, reverse strand). Ensembl gene ENSG00000180638.
Subcellular location: Cell membrane; Apical cell membrane; Apical cell membrane (Isoform 6)
Pathways (Reactome):
Transport of small molecules: SLC-mediated transport of organic cations
Gene Ontology:
Molecular function: antiporter activity; polyspecific organic cation:proton antiporter activity; transmembrane transporter activity; xenobiotic transmembrane transporter activity
Biological process: transmembrane transport; amine transport; proton transmembrane transport; xenobiotic detoxification by transmembrane export across the plasma membrane
Cellular component: apical plasma membrane; plasma membrane; membrane
Genetic constraint (gnomAD): Loss-of-function variants: 52 observed, 66.92 expected, observed/expected ratio (o/e) 0.78, 90% interval 0.62 to 0.98. The upper end of that interval is the gene's LOEUF score, 0.98, which puts it in group 4 of 6, group 1 being the genes least tolerant of losing a copy. Missense variants: 676 observed, 722.83 expected, observed/expected ratio (o/e) 0.94, 90% interval 0.88 to 1. Synonymous variants: 278 observed, 293.87 expected, observed/expected ratio (o/e) 0.95, 90% interval 0.86 to 1.04.
Homologues: Orthologues: chimpanzee SLC47A2 (99% identical), macaque SLC47A2 (88% identical), pig SLC47A2 (77% identical), dog SLC47A2 (76% identical), rabbit SLC47A2 (73% identical), tropical clawed frog slc47a1 (47% identical), zebrafish slc47a1 (42% identical), zebrafish slc47a4 (39% identical). Paralogues in human: SLC47A1 (49% identical).
Diseases named in the same sentence as SLC47A2 in open-access papers:
SLC47A2 is named in the same sentence as 14 diseases in open-access papers, as found by Europe PMC text mining. Sharing a sentence is not in itself a finding about the gene and the disease. The quoted sentences say what the papers report.
type 2 diabetes mellitus (6 papers, 2018 to 2024). A type of diabetes mellitus that is characterized by insulin resistance or desensitization and increased blood glucose levels. "Our data indicated that the AA or GG genotype of SLC47A1 rs2289669 and the AG genotype of SLC47A2 rs12943590 might affect HOMA-IR in patients with type 2 diabetes." (PMID 36289808, 2022). "Finally, the SLC47A2 gene is involved in the excretion of toxic electrolytes in urine and bile, and its rs12943590 SNP has been largely found to be involved in the pharmacodynamics of metformin and pharmacogenetics of type II diabetes mellitus." (PMID 36233078, 2022). "The results of this study showed that SLC47A2 rs12943590 predicted insulin resistance improvement in patients with type 2 diabetes mellitus treated with metformin, which may be helpful to guide the clinical use of metformin in the treatment of type 2 diabetes mellitus to some extent." (PMID 36289808, 2022). "Our study found that the second-order interaction of dose30_g-SLC47A2 rs12943590 might have a significant effect on FINS in patients with type 2 diabetes taking metformin; however, other interaction models were not statistically significant (p > 0.05)." (PMID 36289808, 2022).
anxiety disorder (1 paper, 2025). A category of psychiatric disorders which are characterized by anxious feelings or fear often accompanied by physical symptoms associated with anxiety. "Interestingly, the RPSAP52, SLC47A2, SH3RF3 genes have also been implied in a previous cross-anxiety disorder EWAS." (PMID 40281224, 2025).
Infertility (1 paper, 2025). "rs111749498 (MAF of 2.73%, associated with F-ALL, OR 2.29 (1.72–3.04)) is near SLC47A2, which encodes a multidrug efflux pump that mediates excretion of the drug metformin, commonly used to manage infertility in women with PCOS26." (PMID 40229599, 2025).
Insulin resistance (1 paper, 2022). Increased resistance towards insulin, that is, diminished effectiveness of insulin in reducing blood glucose levels. "The variants of SLC47A1 rs2289669 and SLC47A2 rs12943590 could be predictors of insulin resistance in type 2 diabetic patients treated with metformin." (PMID 36289808, 2022).
SLC47A2 also shares sentences with these, for which no sentence is quoted: cancer (4 papers); breast carcinoma (1); female infertility (1); lactic acidosis (1); liver diseases (1); neurological disease (1); ovarian insufficiency (1); prostate carcinoma (1); renal diseases (1); tumor (1).